BRAF (B-Raf proto-oncogene, serine/threonine kinase)
Diseases named in the same sentence as BRAF in open-access papers (continued):
Sharing a sentence is not in itself a finding about the gene and the disease.
colorectal cancer (continued). "Furthermore, such detailed dietary analysis regarding so many variables has not been previously attempted in relation to mutation of these genes, and as such this report contributes new information to the current knowledge of mutations in BRAF and K-ras in colorectal cancer and dietary intakes." (PMID 20233436, 2010). "Combining anti-EGFR antibodies with BRAF/MEK/ERK pathway blockade opened new treatment options for BRAFV600E-driven colorectal cancer." (PMID 41566838, 2026). "We report a rare case of a BRAF V600E-mutated laterally spreading tumor, granular type (LST-G), with a neuroendocrine carcinoma (NEC) component in a patient with stage IV colorectal cancer." (PMID 41647691, 2026). "In the future, the safety and efficacy of different targeted immunotherapy combination strategies for BRAF V600E-mutant colorectal cancer can be further explored, such as combining BRAF V600E inhibitors with MEK inhibitors and PD-1 monoclonal antibodies." (PMID 41225509, 2025). "Ultimately, using machine learning algorithms and bioinformatics validation, we identified IDO1 as a potential immunotherapy targets for BRAF V600E-mutant colorectal cancer." (PMID 39934467, 2025). "In clinical practice, classic sporadic MSI-H colorectal cancers are predominantly caused by MLH1 promoter methylation and often accompanied by BRAF gene mutations." (PMID 41278281, 2025). "A primary focus is on overcoming therapeutic resistance, particularly in colorectal cancer, where the initial failure of single-agent BRAF inhibitors led to the discovery that feedback activation of EGFR reactivates the pathway." (PMID 41361128, 2025). "We subsequently identified 39 core genes associated with T cell dysfunction and constructed subtypes of BRAF V600E colorectal cancer based on their expression profiles." (PMID 39934467, 2025). "This is a confirmation that BRAF/MEK/PI3K oncogenic signaling involves intrinsic activities highly involved in colorectal cancer progression." (PMID 41009348, 2025). "The actionable colorectal cancer genes KRAS, NRAS, and BRAF were equally mutated in both phenotypes (q-values: 0.49, 0.97, and 0.97, respectively)." (PMID 40702107, 2025). "BRAF class 1–mutant colorectal cancers were significantly more likely to be CMS1 (OR = 6.68; P = 0.024) and significantly less likely to be CMS2 (OR = 0.01; P = 0.01) than cancers in the other two BRAF classes." (PMID 39751654, 2025). "Regarding the genetic profiles of colorectal cancer cell lines used in this study, DLD‐1 harbors a KRAS G13D mutation, and WiDr harbors a BRAF V600E mutation." (PMID 40629930, 2025). "While targeted therapies have shown efficacy in BRAF-mutant colorectal cancer, their role in IHCC remains uncertain." (PMID 40688855, 2025). "Survival analysis of BRAF-mutant colorectal cancer classes: multivariate and univariate mixed-effects Cox proportional hazards models." (PMID 39751654, 2025). "The V600E mutation of BRAF, which drives MEK/ERK signaling, is found in approximately 40% of melanomas and approximately 10% of colorectal cancers." (PMID 40131370, 2025). "Recent research indicates that HSPA8 enhances the progression of BRAF V600E colorectal cancer by activating Wnt/β‐Catenin signalling through CMA‐mediated degradation of CAV1." (PMID 40099939, 2025). "For initial treatment of advanced BRAF-mutated colorectal cancer, combining doublet chemotherapy with anti-EGFR/BRAF therapy offers the best survival benefit." (PMID 41355781, 2025). "A descriptive analysis (n = 166) of the mutational frequency in sporadic colorectal cancer was conducted to explore the prognostic implications of KRAS mutations and the BRAF V600E mutation." (PMID 40647370, 2025). "The analysis revealed significant heterogeneity in the tumor microenvironment composition between BRAF V600E-mutant and wild-type colorectal cancer patients." (PMID 39934467, 2025).
colorectal cancer (continued). "These include Ras signaling, ErbB signaling, NSCLC, AML, pancreatic cancer, colorectal cancer, and renal cancer as a result of treatment resistance mechanisms from the BRAF/MEK/PI3K axis." (PMID 41009348, 2025). "Overall, immune infiltration was significantly higher in BRAF V600E-mutant colorectal cancer, with notably elevated levels of CD8 + T cells, M0 macrophages, and M1 macrophages." (PMID 39934467, 2025). "We additionally subtyped BRAF-mutant colorectal cancers using our own A-B-C positional classifier with consideration for additional Ras status." (PMID 39751654, 2025). "This study constructed novel T cell dysfunction molecular subtypes for BRAF V600E-mutant colorectal cancer and identified IDO1 as a potential immunotherapy target, providing a new strategy for immunotherapy." (PMID 39934467, 2025). "As the research on colorectal cancer continues to deepen, novel prognosis-related variables, including BRAF, RAS gene status, and microsatellite stability, will gradually be identified." (PMID 40756115, 2025). "BRAF inhibitors like encorafenib (Braftovi) and vemurafenib (Zelboraf) are used clinically in colorectal cancer." (PMID 40722718, 2025). "Traditional molecular markers such as BRAF and KRAS mutations are widely used in the diagnosis and treatment of colorectal cancer patients." (PMID 40308511, 2025). "Mutations in BRAF are present in 10-15% of colorectal cancers (CRC), with BRAF V600E being the most common variant." (PMID 40740242, 2025). "There was also a borderline significant difference observed between class 2 and class 3 BRAF-mutant colorectal cancers (frequencies 16.1% and 35.8%, respectively; P = 0.06, Fisher exact test)." (PMID 39751654, 2025). "The response observed in our patient aligns with the biological rationale for simultaneously targeting the BRAF and MEK pathways, a strategy that has already proven effective in BRAF-mutated colorectal cancer." (PMID 40688855, 2025). "Recent genomic studies have revealed distinct prognostic subgroups among BRAF-mutant colorectal cancers, influenced by microsatellite status, tumor location, and immune landscape." (PMID 40761242, 2025). "Oncogenic BRAF mutations, high-level MSI, and proximal location are features frequently associated with colorectal cancer originating from sessile serrated lesions." (PMID 39789100, 2025). "BRAF V600E-mutant colorectal cancer is characterized by high malignancy, resistance to standard treatments, and poor prognosis." (PMID 39934467, 2025). "Studies have shown that BRAF mutations are found in roughly 10–15%, while KRAS mutations are found in about 30–40% of diagnosed colorectal cancer cases." (PMID 40722718, 2025). "Many colorectal cancers acquire driver mutations in genes in the MAPK/ERK signaling pathway, including heterozygous missense changes in KRAS, NRAS, or BRAF." (PMID 39751654, 2025). "Through genomic technology, the identification of specific mutations in genes associated with the development of colorectal cancer, such as KRAS, BRAF, and PIK3CA, can be performed." (PMID 40083375, 2025). "Presently, BRAF and KRAS mutations are significant biomarkers in colorectal cancer classification, primarily because they are reliable predictors of treatment response and prognosis, particularly for anti-EGFR therapy." (PMID 40722718, 2025). "Mutations in BRAF V600E and EGFR T790M significantly influence tumor progression and resistance to treatment, particularly in non-small cell lung cancer and colorectal cancer." (PMID 40283283, 2025). "For example, high-dose vitamin C exhibits anticancer effect in KRAS- and BRAF-mutant colorectal cancer (CRC) cells by promoting ROS accumulation, inducing the S-glutathionylation of GAPDH at Cys152, and inhibiting glycolysis." (PMID 40227215, 2025). "In this study, 637 patients with untreated metastatic BRAF-positive colorectal cancer were randomized to encorafenib/cetuximab (EC), EC + mFOLFOX, or SOC." (PMID 41056448, 2025).
colorectal cancer (continued). "Metastastic disease affects up to 50% of colorectal cancer (CRC) patients and is associated with particularly poor outcomes in the presence of the BRAF V600E mutation." (PMID 39935827, 2025). "In this study, we characterized the tumor microenvironment landscape of BRAF V600E-mutant colorectal cancer using RNA sequencing data, with the reliability of the results strengthened by independent analyses of different datasets." (PMID 39934467, 2025). "For example, we observed genetic interactions between BRAF and EGFR, which is important in the BRAF-mutant colorectal cancer cell line HT-29." (PMID 41353404, 2025). "Immunotherapy is an effective treatment for BRAF V600E-mutant colorectal cancer, but currently, only a few benefit from it." (PMID 39934467, 2025). "Within colorectal cancer, BRAF mutant tumours have higher levels of immune infiltration compared to BRAF wild type." (PMID 40362630, 2025). "Due to the molecular homogeneity of CIMP-high, BRAF-mutant CRCs and serrated colorectal cancer, many studies have used CIMP status and BRAF mutation as molecular markers to identify serrated colorectal cancer." (PMID 40357363, 2025). "Genetic alterations in BRAF are common in colorectal cancer, alongside others like KRAS, which predicts resistance to epidermal growth factor receptor (EGFR) monoclonal antibodies." (PMID 40942081, 2025). "Given that microsatellite instability, BRAF, and RAS mutation status are routinely tested﻿ for colorectal cancers (CRC), studying SARIFA’s additional prognostic value within these molecular subgroups is crucial." (PMID 40340947, 2025). "Given the critical role of BRAF in drug resistance and cancer progression, it remains a key focus in studies exploring targeted treatments for colorectal cancer." (PMID 40942081, 2025). "Caco-2 cells, which are wild-type for BRAF, were chosen because they are well-characterized, differentiated, and representative of the most prevalent form of colorectal cancer." (PMID 40004697, 2025). "In CTC screening, common genetic mutations associated with colorectal cancer include KRAS and BRAF mutations." (PMID 40547026, 2025). "The assay detects the V600E alteration in the BRAF gene using genomic DNA extracted from formalin-fixed, paraffin-embedded colorectal cancer tissue." (PMID 40832988, 2025). "The KRAS and BRAF status holds pivotal significance in tailoring treatment strategies and predicting the prognosis of colorectal cancer (CRC)." (PMID 39220126, 2024). "BRAF-mutant microsatellite-stable colorectal cancer (CRC) with distant metastasis typically carries a poor prognosis." (PMID 38962037, 2024). "This case report presents a unique instance of colorectal cancer brain metastasis harboring both KRAS and BRAF mutations, highlighting its clinical significance and therapeutic challenges." (PMID 39385899, 2024). "For instance, left-sided colorectal cancers are commonly associated with KRAS and BRAF mutations, whereas right-sided cancers are more linked to microsatellite instability and CpG island methylation anomalies." (PMID 38711918, 2024). "Collectively, these results would indicate that oncogenic BRAF regulates sensitivity to BOLD-100 treatment in colorectal cancer." (PMID 39083088, 2024). "Our results highlight the significance of cancer genome profiling tests (CGP tests) and liquid biopsies in guiding treatment strategies for BRAF-mutant colorectal cancer." (PMID 38962037, 2024). "The combined inhibition of PD-1, BRAF, and MEK has been used to treat colorectal cancer patients and organoid models with the BRAFV600E mutation." (PMID 39697234, 2024). "The analysis focused on only three genetic mutations (KRAS, BRAF, EGFR), despite colorectal cancer’s complexity with many potential driver mutations." (PMID 39722096, 2024). "For example, in colorectal cancer, the distinct pattern of immune TME in BRAF-mutated tumors suggested the rationale for using checkpoint inhibitors in this subgroup of patients." (PMID 38397409, 2024).
colorectal cancer (continued). "We previously demonstrated the therapeutic efficacy of encorafenib (BRAF inhibitor) in combination with the epidermal growth factor receptor (EGFR) inhibitor cetuximab for the treatment of patients with advanced colorectal cancer." (PMID 39018564, 2024). "Dual blockade of both EGFR and BRAF has been shown to have synergistic inhibition in BRAFV600E mutant colorectal cancer murine models." (PMID 38203795, 2024). "Patients with colorectal cancer had large frequency of variants in genes APC (50.2%), KRAS (23.2%), BRAF (14.6%), RNF43 (12.3%), and MSH3 (11.3%)." (PMID 39277826, 2024). "Recently, therapeutic approaches developed to inhibit BRAF in multiple myeloma patients have shown success, and similar approaches are being investigated for colorectal cancer patients." (PMID 39722096, 2024). "In the current study, we found that treatment with BOLD-100 resulted in acute increases in ATR/CHK1 phosphorylation, in particular in colorectal cancer cells with activated/oncogenic BRAF signaling." (PMID 39083088, 2024). "BRAF-mutant colorectal cancer is more common in female patients aged ≥70 years or in those with a smoking history, and it is associated with a high rate of peritoneal and distant lymph node metastases and a low rate of lung metastases." (PMID 39529955, 2024). "BRAF alterations are well characterized in patients with colorectal cancer (CRC) but their role in other gastrointestinal (GI) cancers is not known." (PMID 38791902, 2024). "The combination of MTX-531 with mitogen-activated protein kinase kinase or KRAS-G12C inhibitors led to durable regressions of BRAF-mutant or KRAS-mutant colorectal cancer PDX models, resulting in striking increases in median survival." (PMID 38992135, 2024). "Apart from the stage of the tumor, new evidence confirms that people with colorectal cancer (CRC) who have stable microsatellites (MSS) and mutations in BRAF or KRAS genes tend to have worse survival rates." (PMID 39449806, 2024). "Mechanistically, we found that BOLD-100 acutely upregulates CYP1A1 mRNA and ROS levels, particularly in colorectal cancer cells, with activated BRAF oncogene." (PMID 39083088, 2024). "Mutations in both BRAF and KRAS are thought to be mutually exclusive in cases of colorectal cancer despite BRAF's involvement in the KRAS signaling pathway." (PMID 39467702, 2024). "BRAF negativity in this series points to the fact that colorectal cancer etiology and behavior are influenced by other factors." (PMID 39119381, 2024). "Colorectal cancer (CRC) is the second cause of cancer-related death; the CpG-island methylation pathway (CIMP) is associated with KRAS/BRAF mutations, two oncogenes rewiring cell metabolism, worse prognosis, and resistance to classical chemotherapies." (PMID 38540202, 2024). "We found that HAMLET’s inhibitory effect on mitochondrial respiration is cell-type-specific within the context of BRAF mutant colorectal cancer cells." (PMID 38256402, 2024). "There are even conclusions that FURIN is a driver of pro-oncogenes in KRAS and BRAF mutant colorectal cancer." (PMID 39350850, 2024). "Patients with class I V600EBRAF-mutant (MT) colorectal cancer exhibit a poor prognosis, and their response to combined anti-BRAF/EGFR inhibition remains limited." (PMID 39083088, 2024). "A concrete application of ctDNA analysis to identify patients likely to benefit from a given treatment can be found in the study by Ros and colleagues, which looked at colorectal cancer treated with BRAF combination therapies." (PMID 39337479, 2024). "Is rechallenge with anti–epidermal growth factor receptor (EGFR) inhibitors a therapeutic option in patients with refractory circulating tumor DNA (ctDNA) RAS/BRAF wild-type (wt) colorectal cancer (CRC)?" (PMID 38592721, 2024).
colorectal cancer (continued). "The most notable interactions occur between CBD and EGFR, KRAS, BRAF, and MEK1, as reflected by docking scores and being the most critically mutated or dysregulated proteins in colorectal cancer." (PMID 39194723, 2024). "Colorectal cancer (CRC) is the leading cancer among Saudis, and mutations in BRAF, KRAS, and NRAS genes are therapeutically significant due to their association with pathways critical for cell cycle regulation." (PMID 39635441, 2024). "Further, BRAF amplification mediated resistance to MEK and BRAF inhibitors in colorectal cancer cells." (PMID 38919805, 2024). "Colorectal cancer with PIK3CA mutations often accompanies mutations in genes such as KRAS, BRAF, PTEN, AKT1, all of which are components of the PI3K signaling pathway or MAPK signaling pathway." (PMID 39555098, 2024). "On the other hand, BRAF-mutant colorectal cancer is reported to be common in sporadic MSI-high right-sided colon cancers." (PMID 38217014, 2024). "The mitogen-activated protein kinase (MAPK) cascade (RAS/RAF/MEK/ERK) is one of the most dysregulated pathways in human cancers, and one common one is colorectal cancer with KRAS and BRAF mutations." (PMID 39046631, 2024). "In contrast, targeting EGFR in BRAF-mutant colorectal cancer has been successful, underscoring the significance and possibility of a variety of context-dependent mechanisms of MAPK reactivation." (PMID 39001489, 2024). "BRAF V600E attracts wide attention in the treatment of colorectal cancer (CRC) as stratifying and predicting a refractory classification of CRC." (PMID 37973552, 2024). "The combination of MSI and mutation in the BRAF gene is more often observed in patients with stage IV colorectal cancer, but in such cases, it is possible to use targeted therapy with BRAF inhibitors." (PMID 39518386, 2024). "Metastatic colorectal cancers, for example, show a response rate of only 5–10% to BRAF-inhibitors, which has been suggested to be attributed to a higher signaling through EGFR in response to BRAF-inhibitors." (PMID 38716076, 2024). "In lung and colorectal cancer patients who have acquired resistance to EGFR inhibitors, class I BRAF mutations are often detected." (PMID 39529955, 2024). "The validated therapeutic schedule for BRAF inhibitor application in colorectal cancer is based on combining the RAF inhibitor (RAFi) with cetuximab." (PMID 39337479, 2024). "Upregulated heat shock 70 kDa protein 8 (HSPA8) predicts poor prognosis of BRAF V600E colorectal cancer." (PMID 37973552, 2024). "MEK inhibitors are mainly used in BRAF mutant colorectal cancer patients in combination with BRAF inhibitors or other drugs to enhance efficacy and delay resistance." (PMID 39555098, 2024). "RAS, BRAF, and SMAD4 are negatively associated with OS and RFS in patients undergoing curative liver metastasectomy from colorectal cancer." (PMID 39220128, 2024). "ARID1A-deficient expression in colorectal carcinoma is frequently associated with MMR protein deficiency and BRAF mutation and exhibits medullary differentiation and mucinous differentiation." (PMID 38217014, 2024). "Compared with BRAF‐mutated tumors, KRAS c.34G>T mutants showed more frequent LINE‐1 hypomethylation, a biomarker for early‐onset colorectal carcinoma." (PMID 39039804, 2024). "One avenue of investigation emphasizes the need to improve the sensitivity and specificity of BRAF IHC, particularly in colorectal carcinoma biopsy specimens with limited tissue availability." (PMID 39156294, 2024). "This study aimed at determining the frequency of BRAF V600E and KRAS exon 2,3,4 mutations in colorectal carcinoma patients at the Aga Khan University Hospital Nairobi, Kenya." (PMID 39364024, 2024).